CRP (C-reactive protein)
Diseases named in the same sentence as CRP in open-access papers (continued):
Sharing a sentence is not in itself a finding about the gene and the disease.
chorioamnionitis (continued). "Early PTB was strongly associated with placental inflammation, including higher rates of histological chorioamnionitis, composite inflammatory lesions, placental culture positivity, and elevated CRP compared with late PTB." (PMID 42194830, 2026). "While CRP has been investigated concerning severe pregnancy complications such as premature rupture of membranes and chorioamnionitis, there is still limited understanding of low‐grade, subclinical inflammatory processes and related surges of CRP." (PMID 40329709, 2025). "During expectant management, chorioamnionitis is typically monitored using serum inflammatory markers (e.g., leukocyte count, CRP), though cervical interleukin-6 (IL-6) has emerged as a promising local marker." (PMID 41150786, 2025). "C-reactive protein (CRP) is a predictive marker for infection and is associated with an increased incidence of chorioamnionitis." (PMID 38992621, 2024). "In the present study, WBC and CRP were used as reference standards for the prediction of chorioamnionitis." (PMID 38455965, 2024). "Maternal serum iron alteration during pregnancy alone predicted an AUC of 0.532 for chorioamnionitis, compared to an AUC of 0.586 for the conventional indicator CRP and 0.568 for white blood cell count." (PMID 39092027, 2024). "Interleukin (IL-6), CRP, amniotic neutrophil elastase, blood, and vaginal flora serve as biomarkers of chorioamnionitis." (PMID 39574982, 2024). "We then compared the diagnostic accuracy of serum chorioamnionitis miRNA, Lencki criteria (maternal fever, maternal tachycardia, and WBC count), and CRP in all groups." (PMID 39574982, 2024). "which reported that serum CRP has similar accuracy to amniotic fluid index in predicting intra-amniotic infection and/or inflammation among patients with CI or an asymptomatic short cervix." (PMID 38992621, 2024). "In sharp contrast, postnatal CRP levels were significantly increased in the context of maternal clinical chorioamnionitis (p < 0.001)." (PMID 37606448, 2023). "That infant had the second-highest MCP-1 levels within the chorioamnionitis-positive cohort (mean of 2078 mg/dL) as well as elevated IL-6 and CRP values on day 1 (2946 pg/mL and 5.2 mg/dL, respectively)." (PMID 37606448, 2023). "Signs of chorioamnionitis such as raised temperature, fever and elevated leucocyte levels or C-reactive protein (CRP) covered 4.5% of all deliveries, while infections unrelated to delivery, such as urinary tract or ear infection, covered the rest." (PMID 36681812, 2023). "Regarding antenatal infection surveillance and confirmation, based on our results, CRP has value in support of the clinical diagnosis of chorioamnionitis." (PMID 37606448, 2023). "Independent of gestational age, MCP-1 was significantly increased (p < 0.001) in association with maternal preeclampsia, but MCP-1 was decreased (p < 0.01), and CRP was increased (p < 0.01) in the presence of chorioamnionitis with funisitis." (PMID 37606448, 2023). "With the notable exception of pregnancies complicated by chorioamnionitis, the CRP levels we obtained generally paralleled MCP-1 levels." (PMID 37606448, 2023). "They diagnosed chorioamnionitis based on maternal fever (≥38 °C), fundal tenderness, fetal tachycardia, elevated maternal white blood cell count, and C-reactive protein levels." (PMID 37628346, 2023). "By univariate analysis, MCP-1 was decreased (p < 0.01) and CRP was increased (p < 0.05) in infants with signs of chorioamnionitis on pathology." (PMID 37606448, 2023). "C-reactive protein levels in umbilical cord blood were higher in the funisitis group than in the control and chorioamnionitis groups, p < 0.001." (PMID 35626879, 2022). "The higher expression of Gal-3 and IL-1β in these tissues in the PTB group with chorioamnionitis was accompanied by the higher serum levels of the markers of inflammation, fibrinogen, CRP, and the leukocyte number in the maternal and fetal blood at delivery." (PMID 36362749, 2022).
chorioamnionitis (continued). "Associations of MAS with caesarean delivery (p = 0.004), premature rupture of the membranes (p = 0.006), chorioamnionitis (p = 0.007), and higher C-reactive protein levels (p = 0.008) were lost when adjusted for multiple comparisons." (PMID 34408219, 2021). "The aim of this study was to assess and compare the NLR in maternal blood with the white blood cell (WBC) count and C-reactive protein (CRP) concentration for the prediction of histological chorioamnionitis." (PMID 34579660, 2021). "Regarding the prediction of histological chorioamnionitis, the cut-off value was found to be 8.5 mg/L for CRP, 12.62 × 109/L for WBC and 5.97 for NLR." (PMID 34579660, 2021). "Associations of MAS development with caesarean delivery (p = 0.004), premature rupture of the membrane (PROM) (p = 0.006), chorioamnionitis (p = 0.007), and higher C-reactive protein (CRP) levels (p = 0.008) were lost when adjusted for multiple comparisons." (PMID 34408219, 2021). "The white blood cells (WBC) and C-reactive protein (CRP) are inflammatory markers used worldwide for the early diagnosis of chorioamnionitis." (PMID 34579660, 2021). "This is plausible given the observed increase in the concentration of the C-reactive protein (CRP) in the soluble fraction of the amniotic fluid in preterm labor with intra-amniotic infection." (PMID 31945128, 2020). "A recent meta-analysis of 13 studies was conducted to evaluate maternal laboratory predictors of chemical chorioamnionitis including maternal serum CRP and WBC." (PMID 32257148, 2020). "Before using the Kaiser EOS calculator, some providers would treat based on screening laboratory results (such as CBC and CRP), whereas other providers would empirically treat all newborns with exposure to maternal chorioamnionitis." (PMID 31745517, 2019). "In predicting intra-amniotic infection, the area under the curve (AUC) was significantly lower for plasma IL-6 than for AF IL-6 but was similar to that for serum CRP." (PMID 29743041, 2018). "Blood culture, species-specific bacterial real-time PCR, C reactive protein and placental histology for chorioamnionitis and funisitis identified maternal and early newborn infection and inflammation." (PMID 28780500, 2018). "Prediction model for the presence of microbial invasion of the amniotic cavity and histological chorioamnionitis in PPROM below/above 32 weeks of gestation using extreme CRP values." (PMID 26942752, 2016). "At the time of the diagnosis of chorioamnionitis, high CRP (24.6 mg/dl), leukocyte (22.000), sedimentation rate (100 mm/h) and procalcitonin (0.31) levels were found." (PMID 28913037, 2015). "As one of many major laboratory tests, CRP is primarily used when an obstetrician needs to monitor various inflammatory conditions such as chorioamnionitis." (PMID 25291377, 2014). "A further two infants, for whom placental histology was missing, had ≥3 markers of clinical chorioamnionitis: leukocytes > 20,000/μL, CRP > 40 mg/dL, maternal temperature > 38°C, maternal tachycardia > 100 bpm, and fetal tachycardia > 160 bpm." (PMID 25136457, 2014). "With a cut-off of 5 mg/L, the predictive values of CRP for clinical chorioamnionitis were 71% (48, 89%) (sensitivity) and 47% (42, 52%) (specificity), with positive and negative likelihood ratios of 1.4 (1.0, 1.8) and 0.6 (0.3, 1.2)." (PMID 21470433, 2011). "In pPROM group, analysis of procalcitonin concentrations with reference to leucocytosis, serum C-reactive protein, vaginal fluid culture, neonatal infection, histological chorioamnionitis and pPROM-to-delivery interval was carried out.Results." (PMID 17710246, 2007). "The purpose of the study is to evaluate the probability that preterm neonates of mothers with ongoing inflammatory conditions during pregnancy, assessed by measuring conventional inflammatory markers such as CRP, chorioamnionitis, and preeclampsia, develop NEC after birth." (PMID 40295408, 2025).
chorioamnionitis (continued). "Finally, prolonged rupture of membranes and high CRP, WBCs, and PCT levels increased the risk of composite outcome 5 (chorioamnionitis + colonization + early-onset sepsis) by 14%, 11%, and 21%, respectively." (PMID 39857097, 2025). "C-reactive protein (CRP) and Neutrophil-to-Lymphocyte Ratio (NLR) have also been demonstrated as possible diagnostic markers for chorioamnionitis with acceptable diagnostic accuracy that could augment the other diagnostic tools." (PMID 41301672, 2025). "The aim of this study was to evaluate the predictive value of maternal inflammatory status, assessed through biomarkers of inflammation (CRP, chorioamnionitis, preeclampsia), and neonatal inflammatory markers (CRP 1, CRP 2, PCT, IL3, MMP9) on the incidence of NEC in preterm neonates." (PMID 40295408, 2025). "Previous studies reported the use of WBC and CRP to predict unfilled chorioamnionitis." (PMID 38455965, 2024). "However, a recent study demonstrated that maternal serum CRP was a better predictive biomarker of histological chorioamnionitis than PCT." (PMID 37638092, 2023). "However, the results of a systematic review and meta-analysis showed a rather low predicting ability for CRP in the diagnosis of chorioamnionitis." (PMID 37879248, 2023). "The marked increase in CRP following the diagnosis of histopathologic chorioamnionitis with funisitis is consistent with an extensive body of literature and likely reflects the intense inflammation that contributes to the features that are hallmarks of chorioamnionitis." (PMID 37606448, 2023). "In the early stages of chorioamnionitis, infection and inflammation are limited to the chorion and amnion membranes, and IL-6 is released into the maternal blood, leading the mother to produce CRP." (PMID 37919654, 2023). "In our investigation, early postnatal CRP levels were increased in association with not just postnatal infection but also with chorioamnionitis." (PMID 37606448, 2023). "However, results from earlier studies regarding the use of maternal CRP to monitor chorioamnionitis are inconsistent." (PMID 37879248, 2023). "However, there was evidence of maternal systemic inflammation as shown by the elevated WBC and CRP as well as acute histologic chorioamnionitis and acute funisitis." (PMID 37468842, 2023). "Of the variables supporting the presence of intrauterine inflammation and a foetal biochemical response, funisitis and serum α1-AG levels, but not chorioamnionitis or serum CRP and haptoglobin levels, showed robust associations with the development of MAS." (PMID 34408219, 2021). "To date, several studies have identified maternal blood biomarkers that are predictive of histological chorioamnionitis, including various host proteins secreted in response to microbial pathogens, such as serum CRP, MMP-9, IL-6, S100 calcium-binding proteins A8/A9 and IGFBP-1." (PMID 34046191, 2021). "To further investigate the association between S100A gene expression and risk groups, we identified a set of clinical conditions associated with chorioamnionitis and fetal inflammation, namely PTL/PPROM (spontaneous onset of delivery), HCA, FIRS and elevated CRP/IL-6." (PMID 32612607, 2020). "The women in the PTL group with intra-amniotic infection had a significantly lower median gestational age at sampling, higher median serum CRP level, and higher rate of administration of antibiotics and corticosteroids than those in the PTL group without intra-amniotic infection." (PMID 29879190, 2018). "Similarly, our previous study found that serum CRP has a diagnostic performance similar to that of IL-6 and MMP-9 in AF for the detection of histologic chorioamnionitis." (PMID 29743041, 2018). "IA LPS-induced chorioamnionitis is associated with a low-grade fetal inflammatory response, as demonstrated by our observation of elevated SAA3 and CRP mRNA levels in the fetal liver, consistent with previous observations." (PMID 29163213, 2017).
chorioamnionitis (continued). "The major obstetric condition in which determination of maternal serum CRP concentrations might be clinically useful is chorioamnionitis." (PMID 23941472, 2013). "The demonstration of increased CRP, specifically among infants with chorioamnionitis plus funisitis, underscores the importance of cataloging surrogate markers of perinatal inflammation that could signal the need for enhanced surveillance for potential adverse outcomes." (PMID 37606448, 2023). "Importantly, we found that serum CRP (the most used infection/inflammation marker) has a predictive power similar to that of plasma IL-6 for predicting intra-amniotic infection and is similar to that of plasma IL-6 and AF IL-6 for predicting imminent preterm delivery." (PMID 29743041, 2018). "Regarding the prediction of intra-amniotic infection, the following variables were entered into the multivariate logistic regression analysis as significant predictors in the univariate analyses (P < 0.1): gestational age at sampling, serum CRP and plasma IL-6 levels, and cervical length." (PMID 29743041, 2018). "Intrapartum clinical chorioamnionitis, usually diagnosed on the basis of the presence of fever, uterine tenderness, maternal or fetal tachycardia, foul-smelling or purulent amniotic fluid, leucocytosis or elevated C-reactive protein (CRP), is present in 4%–10% of women in labor." (PMID 25105549, 2014). "In order to diagnose intra-amniotic infection, laboratory test results seem to be helpful, including white blood cell (WBC) levels, CRP, procalcitonin (PCT), proinflammatory cytokine concentrations and their increase in control tests." (PMID 41470233, 2025). "Cervical secretion culture outcome was less effective in predicting chorioamnionitis (AUC 0.569) compared to white blood count (WBC) (AUC 0.626) and C-reactive protein (CRP) levels (AUC 0.605)." (PMID 38455965, 2024). "Serum inflammatory markers such as CRP and WBC values are recognized as predictive factors for subclinical chorioamnionitis." (PMID 38977997, 2024). "Our study showed the significant elevation of pro-inflammatory cytokines such as CRP, NLR, MLR, and M% in the blood of patients with chorioamnionitis compared to patients with epidural hyperthermia." (PMID 37919654, 2023). "Previous research has demonstrated that combining CRP and NLR can increase the prognosis accuracy of chorioamnionitis patients." (PMID 37919654, 2023). "Close monitoring for signs of chorioamnionitis (e.g., body temperature, CTG, CRP, leucocytes, IL-6, procalcitonin and amniotic fluid examinations) is necessary to minimize the risk of neonatal and maternal complications." (PMID 36143388, 2022). "CRP and NLR predicted the occurrence of histological chorioamnionitis with AUCs of 0.81 and 0.89, respectively." (PMID 34579660, 2021). "We set out to evaluate the accuracy of maternal blood C-reactive protein (CRP), procalcitonin and interleukin 6 (IL6) in diagnosis of histological chorioamnionitis and/or funisitis (HCA/Funisitis) in PPROM." (PMID 32532314, 2020). "However, an increased CRP could potentially predict future chorioamnionitis development." (PMID 29866067, 2018). "Similar to the results for intra-amniotic infection in the PTL group, low mean gestational age at sampling and high mean serum CRP and CVF VDBP levels were observed in the group of women with PPROM who had intra-amniotic infection." (PMID 29879190, 2018). "Significant bivariate associations for cEOS were present in logistic regression models for ferritin, PCT, SAA, Hp, CRP, and SAP, PROM, clinical chorioamnionitis (chorio), and fetal AI." (PMID 28045978, 2017). "The mean neutrophil counts, CRP levels, and NLR in both the patients with histologic chorioamnionitis (HCA) alone and those with HCA with funisitis were significantly higher than those in women with no placental inflammation." (PMID 25291377, 2014).
chorioamnionitis (continued). "Chorioamnionitis was more frequently diagnosed in women with slightly higher gestational age, primigravida, women with hypertensive disorders of pregnancy, and with a higher level of WBC and CRP on admission." (PMID 39092027, 2024). "The efficacy of CRP, WBC, maternal fever and cervical secretion cultures results in predicting chorioamnionitis was examined using ROC curves with the gold standard of a confirmed diagnosis of chorioamnionitis by placental chorioamnionitis pathology." (PMID 38455965, 2024). "CRP is a nonspecific biomarker during the inflammation process and has been widely used to monitor various inflammatory conditions including chorioamnionitis." (PMID 37879248, 2023). "As the presence of chorioamnionitis is considered the most important factor that determines prognosis in PPROM, many studies have focused on its early and noninvasive detection, including some on white blood cells (WBCs) and C-reactive protein (CRP)." (PMID 37163192, 2023). "Furthermore, baseline characteristics between the preterm and term groups were similar, except for the presence of chorioamnionitis, PPROM, elevated CRP and mode of delivery (favoring C-section) in the preterm groups." (PMID 36578660, 2022). "For example, intra-amniotic infection can cause SPTB; however, we only checked for the presence or absence of sludge, serum CRP, and cervical elastase." (PMID 34987587, 2021). "Older reviews suggested CRP is useful in diagnosis of chorioamnionitis, but more recent systematic reviews give no clear evidence for this recommendation." (PMID 32532314, 2020). "In a retrospective evaluation of 73 women with PPROM investigators found that maternal CRP levels were not effective in predicting chorioamnionitis." (PMID 29866067, 2018). "In predicting intra-amniotic infection, the AUC for plasma IL-6 was significantly lower than that for AF IL-6 (P < 0.001), but was not different from the AUC for serum CRP (P = 0.414)." (PMID 29743041, 2018). "Maternal CRP (P = 0.000016) and white cell count (WCC) (P = 0.0016, Mann–Whitney U) were elevated in patients with chorioamnionitis with funisitis and both were significantly correlated with vaginal bacterial alpha diversity (WCC; rho = 0.54, P = 0.0001 and CRP; rho = 0.45, P = 0.0013)." (PMID 29361936, 2018). "This study evaluated maternal C-reactive protein (CRP) as a predictor of microbial invasion of the amniotic cavity (MIAC) and histological chorioamnionitis (HCA) in women with preterm prelabor rupture of the membranes (PPROM) before and after 32 weeks of gestation." (PMID 26942752, 2016). "Maternal C-reactive protein (CRP) is no accurate predictor of clinical or histological chorioamnionitis (CAM)." (PMID 26121653, 2015). "Except for CRP levels in villitis, on which data seem scarce, even if some studies report CRP’s significance in predicting chorioamnionitis, several other studies conclude that it does not seem to be an effective independent predictor of clinical or histologic chorioamnionitis." (PMID 37873776, 2023). "An extended duration of premature membrane rupture (PROM) and markers of maternal infection, such as elevated C-reactive protein and elevated body temperature (above 38 °C), were more frequently observed in the funisitis group than in the control and chorioamnionitis groups (data not shown)." (PMID 35626879, 2022). "Bullen and colleagues demonstrated that CRP levels were non-significantly elevated for preterm (5.5 μg/ml) versus term deliveries (4.8 μg/ml) and were higher in the preterm deliveries with histologic chorioamnionitis (6.3 μg/ml)." (PMID 32309764, 2020). "However, owing to its lack of specificity, the utility of CRP as a biomarker of occult PM requires further investigation in studies that include other common infections in pregnancy such as chorioamnionitis." (PMID 22174834, 2011).